NASP (nuclear autoantigenic sperm protein)
Description:
Component of the histone chaperone network. Binds and stabilizes histone H3-H4 not bound to chromatin to maintain a soluble reservoir and modulate degradation by chaperone-mediated autophagy. Required for DNA replication, normal cell cycle progression and cell proliferation. Forms a cytoplasmic complex with HSP90 and H1 linker histones and stimulates HSP90 ATPase activity. NASP and H1 histone are subsequently released from the complex and translocate to the nucleus where the histone is released for binding to DNA. [Isoform 1]: Stabilizes soluble histone H3-H4. [Isoform 2]: Stabilizes soluble histone H3-H4.
Synonyms: FLB7527; FLJ31599; FLJ35510; MGC19722; MGC20372; MGC2297; DKFZp547F162; PRO1999; HMDRA1
Tractability: PROTAC: UniProt records ubiquitination sites on it; ubiquitination databases record sites on it; its protein half-life has been measured.
Gene: Protein-coding gene on chromosome 1 (45,583,581 to 45,618,905, forward strand). Ensembl gene ENSG00000132780.
Subcellular location: Cytoplasm; Nucleus
Subcellular location (Human Protein Atlas): Nucleoplasm
Gene Ontology:
Molecular function: histone binding; protein binding
Biological process: DNA replication-dependent chromatin assembly; blastocyst development; male gonad development; response to testosterone
Cellular component: chromatin; nucleoplasm; protein-containing complex; cytoplasm; nucleus
Genetic constraint (gnomAD): Loss-of-function variants: 20 observed, 73.76 expected, observed/expected ratio (o/e) 0.27, 90% interval 0.19 to 0.39. The upper end of that interval is the gene's LOEUF score, 0.39, which puts it in group 1 of 6, group 1 being the genes least tolerant of losing a copy. Missense variants: 763 observed, 836.33 expected, observed/expected ratio (o/e) 0.91, 90% interval 0.86 to 0.97. Synonymous variants: 273 observed, 294.27 expected, observed/expected ratio (o/e) 0.93, 90% interval 0.84 to 1.03.
Homologues: Orthologues: chimpanzee NASP (99% identical), macaque NASP (96% identical), dog NASP (89% identical), rabbit NASP (86% identical), pig NASP (83% identical), mouse Nasp (81% identical), rat Nasp (80% identical), tropical clawed frog nasp (36% identical), zebrafish nasp (36% identical), Drosophila melanogaster Nasp (17% identical), Caenorhabditis elegans nasp-1 (14% identical).
Diseases named in the same sentence as NASP in open-access papers:
NASP is named in the same sentence as 26 diseases in open-access papers, as found by Europe PMC text mining. Sharing a sentence is not in itself a finding about the gene and the disease. The quoted sentences say what the papers report.
glioma (3 papers, 2021 to 2024). A benign or malignant brain and spinal cord tumor that arises from glial cells (astrocytes, oligodendrocytes, ependymal cells). "Next, we examined the association between NASP expression and glioma grade and found that NASP mRNA expression levels were higher in grade 4 than in grade 2 or 3 gliomas in both the TCGA and Chinese Glioma Genome Atlas (CGGA) cohorts." (PMID 38605477, 2024). "Moreover, high expression of NASP was associated with a poor prognosis, further proving that NASP may play an important role in the malignant progression of gliomas." (PMID 38605477, 2024). "In the current studies, we investigated the expression level of NASP in glioma (LGG and GBM) and its relationship with patient prognosis." (PMID 38605477, 2024). "NASP was highly expressed in gliomas, and its expression was negatively correlated with the prognosis of glioma." (PMID 38605477, 2024). "Western blot analysis revealed that the protein expression levels of NASP were positively correlated with the WHO glioma grade." (PMID 38605477, 2024). "To explore the effects of NASP expression on the survival time of patients with glioma, we analyzed the survival data obtained from the TCGA and CGGA databases and the data of 232 patients with glioma collected in our hospital." (PMID 38605477, 2024). "To investigate the role of NASP in glioma development, we first compared the expression of NASP across different types of tumor tissues and the corresponding normal tissues by using The Cancer Genome Atlas (TCGA) database." (PMID 38605477, 2024). "We analyzed and verified the expression of nuclear autoantigenic sperm protein (NASP) in gliomas and its relationship with patient prognosis." (PMID 38605477, 2024). "To explore whether the protein expression levels of NASP in gliomas were consistent with their mRNA expression levels, we randomly selected nine glioma tissues of different grades and extracted the total protein content of these tissues." (PMID 38605477, 2024). "As expected, NASP mRNA expression levels were the highest in the grade 4 glioma samples." (PMID 38605477, 2024). "Our study firstly established a seven-gene signature comprising METTL3, COL18A1, NASP, PHLPP2, TIMP1, U2AF2, and VEGFA with a good capability for predicting survival in glioma." (PMID 34589481, 2021). "The results showed that the expression levels of NASP were higher in various tumor tissues, including LGG and GBM, than in the corresponding normal tissues, suggesting that NASP plays a role in the malignant progression of glioma." (PMID 38605477, 2024). "Our study established and validated a seven-gene signature comprising METTL3, COL18A1, NASP, PHLPP2, TIMP1, U2AF2, and VEGFA, with a good capability for predicting glioma survival, which may guide therapeutic customization and clinical decision-making." (PMID 34589481, 2021). "Collectively, m6A RNA methylation regulators KIAA1429, METTL16, METTL3, IGF2BP2, and YTHDF, and targets NASP, TIMP1, U2AF2, COL18A1, and VEGFA could serve as oncogenes in glioma, while PHLPP2 is a tumor suppressor." (PMID 34589481, 2021). "To determine the influence of NASP expression levels on the radiotherapy response of patients with LGG and GBM, we compared the overall survival rates among patients with glioma in the CGGA database who received radiotherapy but not temozolomide chemotherapy." (PMID 38605477, 2024).
prostate carcinoma (3 papers, 2011 to 2025). A carcinoma that arises from epithelial cells of the prostate gland. "Previous studies have shown that NASP promotes the proliferation of various human cancer cells, including hepatocellular carcinoma, prostate cancer, melanoma, and gastric cancer, and can be used as a marker of poor prognosis." (PMID 38605477, 2024). "NASP codes for nuclear autoantigenic sperm protein isoform 2 a histone H1 binding protein expressed in all dividing cells, inhibits proliferation and induces apoptosis in prostate cancer PC-3 cells, and is one of the hub genes involved in maintaining stem cell fate." (PMID 21915259, 2011).
breast carcinoma (2 papers, 2021 to 2025). "In this study, we compared the expression of NASP among breast cancer subtypes and discovered that NASP was only highly expressed in TNBC." (PMID 40612673, 2025). "NASP, nuclear autoantigenic sperm protein, has become an important constituent of “poor prognosis signature” in breast cancer patients." (PMID 33510252, 2021). "In addition, the IHC analysis in the Human Protein Atlas showed that the expression of NASP protein was higher in breast cancer tissue than in mammary gland." (PMID 40612673, 2025). "However, the role of NASP in different breast cancer subtypes was not clear, and how tNASP affected breast cancer was ignored." (PMID 40612673, 2025).
gastric cancer (2 papers, 2017 to 2024). A primary or metastatic malignant neoplasm involving the stomach. "Most of the gastric cancer cell lines have an increase in the levels of NASP protein level compared with GES-1." (PMID 28173777, 2017). "In summary, we have clarified a novel pathway regulating cell proliferation in gastric cancer, which is, miR-29c inhibits cell proliferation, promotes apoptosis and arrests cell cycle at G1/G0 phase by targeting NASP." (PMID 28173777, 2017). "Our study suggests one mechanism that contributes to the elevated NASP levels in tumors is a deregulation of miR-29c and further supports targeting NASP as a therapeutic strategy in gastric cancer." (PMID 28173777, 2017). "Taken together, these data provide evidence that the function of miR-29c inhibit cell proliferation in gastric cancer is at least partially through targeting NASP." (PMID 28173777, 2017). "Since miR-29c down-regulated NASP to suppress cell proliferation, induce cell apoptosis and cause cell cycle arrest in G1/G0, it is reasoned that specific knockdown of NASP could elicit similar phenotypes induced by miR-29c in gastric cancer." (PMID 28173777, 2017). "Moreover, we measured miR-29c expression and NASP protein level in 4 pairs of gastric cancer and matched normal tissues." (PMID 28173777, 2017). "Next, we evaluated NASP protein level in GES-1 and nine gastric cancer cell lines by Western blot analysis." (PMID 28173777, 2017).
hepatocellular carcinoma (2 papers, 2024 to 2025). A malignant tumor that arises from hepatocytes. "In hepatocellular carcinoma, NASP antagonized the chromatin accessibility and promoted tumorigenesis." (PMID 40612673, 2025).
melanoma (2 papers, 2024 to 2025). A malignant, usually aggressive tumor composed of atypical, neoplastic melanocytes. "Conversely, increased NASP expression has been shown to promote melanoma cell proliferation by accelerating the G1/S phase transition of the cell cycle, and high levels of NASP are predictive of shorter overall survival and higher recurrence rates in patients with melanoma." (PMID 38605477, 2024).
chronic osteomyelitis (1 paper, 2023). "These are needed to determine if this newly identified and partially characterized NASP class C contributes to the pathogenicity of S. aureus in chronic osteomyelitis." (PMID 37433170, 2023).
COVID-19 (1 paper, 2022). A disease caused by infection with severe acute respiratory syndrome coronavirus 2. "DNMT3B, LAMC1, MET, NASP, PTEN, and SPARC are upregulated in COVID-19." (PMID 36204652, 2022). "However, the roles of LAMC1, MET, NASP, and SPARC in COVID-19 have not yet been elucidated." (PMID 36204652, 2022).
glioblastoma (1 paper, 2024). The most malignant astrocytic tumor (WHO grade IV). "Nuclear autoantigenic sperm protein (NASP) plays a crucial role in glioblastoma progression and radioresistance, promotes DNA repair, and activates the STAT3 signaling pathway through ANXA2." (PMID 38605477, 2024).
liver cancer (1 paper, 2021). An epithelial or non-epithelial malignant neoplasm that arises from the liver. "NASP levels in liver tumors are generally higher than those in normal liver tissues, and NASP down-regulation inhibits liver cancer cells from forming tumors." (PMID 34301312, 2021).
lymphoma (1 paper, 2023). A malignant (clonal) proliferation of B- lymphocytes or T- lymphocytes which involves the lymph nodes, bone marrow and/or extranodal sites. "Interestingly, PcG proteins, commonly considered as drivers of lymphomas acting as a recruitment platform for DNA methylation, and NASP, over-expressed in various cancers, were decreased after N3a-treatment." (PMID 37568720, 2023).
ovarian carcinoma (1 paper, 2013). A malignant neoplasm originating from the surface ovarian epithelium. "NASP belongs to a network of genes important for cell survival, and NASP protein is a tumour-associated antigen in ovarian cancer." (PMID 23935626, 2013).
renal cell carcinoma (1 paper, 2017). "Previous studies have investigated the role of NASP in renal cell carcinoma." (PMID 28173777, 2017).
cancer (12 papers, 2009 to 2024). A tumor composed of atypical neoplastic, often pleomorphic cells that invade other tissues. "The histone chaperone NASP has two splice variants: tNASP, which is found in cancer, embryonic and germ cells, and sNASP, found in embryonic and somatic cells." (PMID 35037039, 2022). "Two splice variants of NASP have been reported: testicular NASP (tNASP), which is mainly expressed in testis, stem cells, embryonic tissues and malignant tumors; somatic NASP (sNASP), which exists in all somatic mitosis cells." (PMID 28173777, 2017). "Transcribed from a single copy gene, NASP has two splice variants: tNASP, which is found in cancer, transformed, embryonic and germ cells and sNASP, which is found in embryonic and somatic cells." (PMID 21496299, 2011). "Whilst the somatic NASP splice isoform is expressed ubiquitously, the NASP-T splicing isoform has a much tighter anatomic distribution and its splicing is associated particularly with cancer cells and embryonic development." (PMID 23935626, 2013). "In humans NASP expression has been reported to be significantly altered in many cancers including prostrate." (PMID 29661843, 2018). "In humans, NASP expression is significantly altered in a variety of cancers including those of the ovary and prostate." (PMID 24951090, 2014). "In humans, growing evidence implicates NASP miss-regulation in the development of a variety of cancers." (PMID 24951090, 2014). "NASP has been detected in all dividing cells, but only cancer, transformed, germ, and embryonic cells have a high level of expression of the tNASP splice variant." (PMID 21496299, 2011). "NASP expression is characteristic of all dividing cells, but only cancer, germ, embryonic and transformed cells have a high level of expression of the tNASP splice variant." (PMID 21496299, 2011). "Higher levels of NASP protein expression might be needed by cancer cells to enable their higher rates of replication to be achieved." (PMID 23935626, 2013). "Gene ontology, molecular network and canonical pathway analysis of NASP overexpression demonstrated that the most significant changes were in proteins participating in organismal injury, immune response, and cellular growth and cancer pathways (major "hubs": TNF, FOS, EGR1, NFκB, IRF7, STAT1, IL6)." (PMID 19439102, 2009). "Collectively, our findings suggest that the NASP/ANXA2/STAT3 axis is a potential therapeutic target for improving the prognosis of patients with GBM, which has important implications for the development of more effective and precise cancer treatments." (PMID 38605477, 2024). "Although NASP has been reported to be an important prognostic marker in prostate cancer cells, it is not clear if tNASP has a specific role is this cancer." (PMID 21496299, 2011). "Networks with cancer-related functions had the highest significance, however reproductive networks containing follistatin and FSH were also significantly affected, which confirmed NASP's important role in reproductive tissues." (PMID 19439102, 2009).
tumor (9 papers, 2013 to 2025). "The results of RT-qPCR suggested that NASP expression was significantly higher in tumor tissues than in paired adjacent tissues." (PMID 40612673, 2025). "The results showed that compared to paired adjacent tissues, NASP protein was highly expressed in TNBC tumor tissues." (PMID 40612673, 2025). "In a cell model, NASP overexpression promoted the activation of DNA repair pathways and repair of DNA damage, which increased the clonogenic ability of tumor cells after radiotherapy." (PMID 38605477, 2024). "Collectively, these results strongly suggest that elevated NASP expression in GBM contributes to poor clinical outcomes by reducing tumor radiosensitivity." (PMID 38605477, 2024). "In summary, we demonstrated that NASP promotes tumor progression and radioresistance and provides a plausible molecular mechanism involving ANXA2 phosphorylation and nuclear translocation, as well as enhanced STAT3 signaling, which promotes radioresistance and enhances tumorigenic behavior." (PMID 38605477, 2024). "In the deep region of the tumor, 14-3-3 protein theta and Galphai2 correlated positively with the advancement of the Dukes stage, while beta ig-h3, nuclear autoantigenic sperm protein (NASP), and V-set-immunoglobulin domain-containing protein 2 (VSIG2) exhibited negative correlation." (PMID 39195201, 2024). "A similar result was obtained by analysing the GSE121248 and GSE33006 datasets from the GEO database, and nearly all H3–H4 histone chaperones were significantly overexpressed in tumor tissues, except for APLF, HIRA and NASP." (PMID 38561384, 2024). "In present study, we indicate that miR-29c acts as a tumor suppressor by suppressing cell growth through CCK-8 and colony formation assays, promotes apoptosis and arrests cell cycle at G1/G0 stage by targeting NASP." (PMID 28173777, 2017). "Additionally, NASP may activate the STAT3 pathway through p‐ANXA2, which, in turn, promotes radioresistance and tumor progression." (PMID 38605477, 2024). "In addition, we demonstrated the molecular mechanism by which NASP mediates DNA repair through ANXA2 in GBM, and observed the effect of combination treatment with the STAT3 pathway inhibitor, WP1066, and radiotherapy in tumor‐bearing mice models." (PMID 38605477, 2024).
infection (1 paper, 2017). The state of being infected such as from the introduction of a foreign agent such as serum, vaccine, antigenic substance or organism. "The result from Western blot was confirmed that the protein level of NASP was indeed down-regulated in SGC-7901-RV-miR-29c cells, and the NASP mRNA level still had no change after RV-miR-29c infection." (PMID 28173777, 2017).
NASP also shares sentences with these, for which no sentence is quoted: Alzheimer disease (1 paper); asthma (1); autoimmune disease (1); colon cancer (1); colorectal cancer (1); lung diseases (1); lupus (1); renal carcinoma (1); reproductive system disease (1); viral infection (1).